C5 (complement C5)
Diseases named in the same sentence as C5 in open-access papers (continued):
Sharing a sentence is not in itself a finding about the gene and the disease.
paroxysmal nocturnal hemoglobinuria (continued). "Namely, Eculizumab (a monoclonal antibody targeting protein C5) has been used to treat paroxysmal nocturnal hemoglobinuria (PNH) patients." (PMID 27147970, 2016). "In May 2021, pegcetacoplan was approved by the US FDA to treat adults with paroxysmal nocturnal hemoglobinuria (PNH), and it is the first to target C3, a complement component upstream of C5." (PMID 36671244, 2022). "The standard procedure for patients with paroxysmal nocturnal hemoglobinuria (PNH) with significant clinical symptoms is the humanized monoclonal antibody eculizumab (Soliris), which binds to C5 and blocks the terminal complement pathway and was approved in 2007." (PMID 36362117, 2022). "Despite growing interest, the development of complement-targeted drugs has been slow, with two related anti-C5 antibodies (eculizumab, ravulizumab) approved for the treatment of paroxysmal nocturnal hemoglobinuria (PNH) and other indications long remaining the only clinical options." (PMID 36127336, 2022). "Another study using Soliris (Eculizumab), an FDA-approved C5 inhibitor, for the treatment of paroxysmal nocturnal hemoglobinuria (PNH) has shown that Eculizumab application in a septic child rescued the sepsis-induced multiorgan failure, including cardiac dysfunction." (PMID 32194424, 2020). "Eculizumab, the humanized monoclonal IgG2/4-antibody targeting C5, was the first complement drug available in the clinic, approved by the Food and Drug Administration (FDA) for the treatment of paroxysmal nocturnal hemoglobinuria (PNH) in 2007." (PMID 32457738, 2020). "Eculizumab, a monoclonal antibody directed against C5 and the first complement blocker to be approved by the FDA for treatment of paroxysmal nocturnal hemoglobinuria and aHUS, drastically improved hemolysis and renal survival in those patients." (PMID 31766155, 2019). "Eculizumab, a humanized monoclonal antibody that blocks the cleavage of C5, has demonstrated clinical efficacy in the treatment of complement-mediated diseases such as paroxysmal nocturnal hemoglobinuria (PNH), atypical hemolytic uremic syndrome (aHUS), and generalized myasthenia gravis." (PMID 30592762, 2018). "The currently utilized anti-C5 antibody in paroxysmal nocturnal hemoglobinuria, eculizumab, targets MG7 domain in α-chain, preventing the interactions between C5 and C5 convertases." (PMID 28477014, 2017). "Eculizumab (anti-C5 antibody) is an example of an FDA- and EMA-approved complement-inhibitory drug to treat patients suffering from paroxysmal nocturnal hemoglobinuria, atypical hemolytic uremic syndrome, generalized myasthenia gravis, and neuromyelitis optica spectrum disorder." (PMID 38817607, 2024). "The objective of this analysis was to identify risk factors for thromboembolic events (TE) in patients with paroxysmal nocturnal hemoglobinuria (PNH) who were not treated with C5 inhibitors." (PMID 37668788, 2023). "For example, C5-inhibitor ECU, which has clinical efficacy in diseases such as paroxysmal nocturnal hemoglobinuria, atypical hemolytic uremic syndrome, generalized myasthenia gravis, and neuromyelitis optica spectrum disorder, is also increasing the risk for meningococcal infections." (PMID 34899737, 2021). "ECU is a monoclonal anti-C5 antibody which inhibits C5 activation, thus blocks the terminal pathway of the complement system irrespective of lacking CD55 and CD59 on peripheral blood cells and is most effective in paroxysmal nocturnal hemoglobinuria (PNH)." (PMID 24086391, 2013). "These are eculizumab, an anti-C5 antibody, approved for AQP4+ NMOSD, generalized MG, as well as atypical hemolytic uremic syndrome (aHUS) and paroxysmal nocturnal hemoglobinuria (PNH)." (PMID 36032156, 2022). "The approval of the complement-targeting anti-C5 antibody, eculizumab, by the United States Food and Drug Administration (FDA) for the rare disease paroxysmal nocturnal hemoglobinuria (PNH) in 2007 has led to a renaissance in complement therapeutics." (PMID 31632397, 2019).
paroxysmal nocturnal hemoglobinuria (continued). "Unlike C5 inhibitors, Voydeya effectively prevents the deposition of C3b fragments on red blood cells in patients with paroxysmal nocturnal hemoglobinuria (PNH)." (PMID 40430547, 2025). "C5 inhibitors play a critical role in preventing the formation of the membrane attack complex (MAC), offering effective solutions for conditions like atypical hemolytic uremic syndrome (aHUS) and paroxysmal nocturnal hemoglobinuria (PNH)." (PMID 40731834, 2025). "Inhibiting activation of C5, and thus the generation of C5a and MAC, has shown great therapeutic benefit in complement-driven inflammatory diseases, such as atypical hemolytic uremic syndrome (aHUS) and paroxysmal nocturnal hemoglobinuria (PNH)." (PMID 31871188, 2020).
COVID-19 (83 papers, 2020 to 2025). A disease caused by infection with severe acute respiratory syndrome coronavirus 2. "This has led to clinical trials targeting, for example, complement C5 with Ravulizumab and testing its effect on COVID-19-associated lung injuries and distress." (PMID 38715618, 2024). "C5 inhibition in COVID-19, for example, is associated with an increased risk of secondary infections, whereas targeting C5a does not presumably due to the preservation of the MAC." (PMID 37332066, 2023). "Hypotheses from other contexts, such as COVID-19, propose that upstream C3 blockade may exert broader immunological effects than terminal C5 inhibition, potentially influencing viral susceptibility." (PMID 40860872, 2025). "Based on our results, we propose that COVID-19 patients at high risk for immunothrombosis could be identified via elevated complement markers such as C5." (PMID 37239041, 2023). "This activity was translated into a marked disease-modifying effect in the Syrian golden hamster model of COVID-19 with treated animals showing minimal weight loss and very limited pulmonary infection and associated changes following a single dose of C5 trimer 24 h post virus challenge." (PMID 34552091, 2021). "We propose that COVID-19 at high risk for immunothrombosis could be identified by complement C5." (PMID 37239041, 2023). "Yet SARS-CoV-2 can also induce activation of the complement cascade, with COVID-19 patients having elevated C5 levels in particular." (PMID 40815262, 2025). "Various targeted complement therapeutics, including anti-C5a monoclonal antibodies, anti-C5 monoclonal antibodies, and C3 inhibitors, have demonstrated promising efficacy in clinical studies for both COVID-19 and sepsis." (PMID 41567206, 2025). "In particular, the anti-C5 antibody eculizumab has shown positive effects in severe COVID-19 patients across various institutions." (PMID 38368584, 2024). "Studies have shown that C5 inhibitors are anti-inflammatory in COVID-19 critically ill patients and decreased neutrophil counts and attenuated NET release." (PMID 38165570, 2024). "The anti-C5 monoclonal antibody eculizumab has been used in COVID-19 patients, but a study evaluating the longer-acting anti-C5 monoclonal antibody ravulizumab was discontinued early due to lack of efficacy." (PMID 39202695, 2024). "Conditional C3 or C5 knockout mice are useful to dissect the role of local complement activation and production in the COVID-19 pathogenesis." (PMID 38368584, 2024). "Levels of C5a and C5 were raised in COVID-19 patients, thereby offering a rationale for C5 inhibitor therapy in COVID-19; this is reported in the results of the CORONET study." (PMID 37731491, 2023). "The expression levels of CLDN5, c1qRs, and C5 have been found to be altered in endothelial cells in COVID-19 patients, which has also been reported to play a role in endothelial dysfunction." (PMID 37239234, 2023). "Complement-mediated lung injury plays a key role in COVID-19 pneumonia, and preliminary results hint at the usefulness of a C5 inhibitor in COVID-19 recovery." (PMID 37731491, 2023). "The C5 complement inhibitor eculizumab also shows beneficial effects in patients with severe COVID-19." (PMID 36166068, 2023). "Children with acute COVID-19 had significantly elevated levels of C1q, C2, C4, C3, C5, C5a, C3b, factor B, factor H, and factor I in comparison with convalescent COVID-19 children." (PMID 36961465, 2023). "All studies have been designed to address the safety and efficacy of the complement inhibition by targeting C1q/MBL, C3, or C5 in COVID-19-induced ALI/ARDS." (PMID 37006238, 2023). "In Covid-19 patients with at least 6 days of symptoms, zilucoplan effectively inhibited the formation of sC5b-9, most likely via blocking C5 activation in the lungs, the site most inflamed in COVID-19." (PMID 35945604, 2022). "The usefulness of complement factors (C3, C5, C5a, sC5b-9) as biomarkers for COVID-19 has been suggested by several groups." (PMID 33982161, 2022).
COVID-19 (continued). "Complement inhibition against COVID-19 can improve symptoms and reduce mortality by reducing inflammation and preventing lung injury, especially for C3, C5, and C5a." (PMID 36405695, 2022). "The inhibition of C3 and C5 also increased platelet counts in patients with thrombocytopenia induced by COVID-19 and reduced the incidence of thrombosis." (PMID 35204727, 2022). "One explanation is that blockade of C5aR1 alone is not sufficient to halt the detrimental effects of complement in COVID-19 since C5b-9 is still formed or because C5 can still signal through alternative receptors." (PMID 35945604, 2022). "Some of these pathways, including allograft rejection, autoimmune diseases (IBD, SLE, T1D, AITD, RA), C3/C4/C5 complement system and COVID-19, overlapped across headache and thyroid traits." (PMID 36672757, 2022). "The complement system plays a role in the pulmonary inflammation phenotype occurring in SARS-CoV-2 patients, with several C3 and C5 inhibitors offering rapid clinical benefits for COVID-19 patients within three days." (PMID 36614003, 2022). "Consistent with our study, other reports also revealed that activation of complement C3 and C5 was involved in the pathogenesis of COVID-19." (PMID 33557911, 2021). "We recruited 135 COVID-19 patients and measured plasma levels of C5, C3, cell-free DNA and myeloperoxidase (MPO)-DNA." (PMID 33557911, 2021). "Numerous randomized controlled trials reported increased survival in severe cases of COVID-19 patients treated with anti-C5 therapy." (PMID 34276659, 2021). "In this study, we investigated the longitudinal dynamics of complement C3, C5 and NETs in the plasma of mild and severe patients with COVID-19." (PMID 33557911, 2021). "The levels of C3 and C5 were further raised to 56.23 [31.91, 76.04] mg/mL and 326.1 [245, 388.8] μg/mL in the severe COVID-19 patients." (PMID 33557911, 2021). "In the late stages of COVID-19, inhibiting the abnormal activation of complement (C3 and C5) can widely control ARDS, and also control the systemic inflammation affecting the microvascular bed of the kidneys, brain and other important organs in severe cases." (PMID 34321065, 2021). "Inhibitors of the complement cascade, such as complement C5 inhibitors and P-selectin inhibitors, are under investigation in randomized clinical trials for the treatment of COVID-19 patients." (PMID 34769508, 2021). "C5 inhibiting therapeutics, Eculizumab and Ravulizumab, used to treat aHUS patients were beneficial in combating COVID-19 in four patients." (PMID 34944087, 2021). "Early clinical reports indicates that C3 inhibition therapy holds potential anti-inflammatory properties in COVID-19 and anti-complement C5 therapy in patients with severe COVID-19 lead to a drop in inflammatory markers and a successful recovery." (PMID 34335279, 2021). "The first result of anti-C5 treatment has also revealed a rapid and promising effect on COVID-19 patients." (PMID 33907513, 2021). "In this study, we report the persistent presence of high levels of circulating complement C5a, a cleavage product of terminal complement C5, in COVID-19 patients with a long hospital stay, even weeks after hospital discharge." (PMID 34868021, 2021). "In particular, the CS has gained attention as a potential therapeutic target in COVID-19 patients, and first experiences targeting C3 and C5 of the complement system have been published." (PMID 32922409, 2020). "These early results demonstrate not only the role of complement in COVID-19, but the utility of C3 and C5 as therapeutic targets to improve patient outcomes." (PMID 33374356, 2020). "Ravulizumab-cwvz is a long-acting C5 complement inhibitor with an upcoming phase III clinical trial for COVID-19 severe pneumonia." (PMID 33374356, 2020). "In addition, C5 was identified as an upstream regulator of the COVID-19 umbilical cord transcriptomics profile, indicating the upregulation of a panel of downstream C5-induced inflammatory mediators (Fig. EV1D,E)." (PMID 39390219, 2024).
COVID-19 (continued). "Tesidolumab, which binds to a separate C5 epitope, and ravulizumab, which shares the same epitope on C5 with eculizumab but has longer plasma stability, have also been investigated in preliminary single-arm studies of severe COVID-19 patients." (PMID 38368584, 2024). "While no common biomarker was identified to be affected in all four specimen types (Fig. EV2A,B), we observed that complement factors—C1q, C4, and C5 were commonly induced in in cord plasma and amniotic fluid specimens derived from COVID-19 pregnancies (Fig. EV2A)." (PMID 39390219, 2024). "In COVID-19 the complement (C3 and C5) is the mediator for developing inflammation." (PMID 36901751, 2023). "However, a statistical correlation between complements C3, C5, and C5b-9 in COVID-19 patients with established clinical scores of SOFA and SAPSII has not yet been described." (PMID 37239041, 2023). "The complement proteins C1q, C2, C4, C4b, MBL, C5, C5a, C3, C3b and complement factors such as factor B, factor D, factor H, and factor I were significantly enhanced in children with severe or moderate COVID-19 (eFigure 3, eTable 5, eTable 6 in Supplement 1)." (PMID 36961465, 2023). "In addition, clinical trials with complement inhibitors targeting either C5 or C3 in the treatment of severe COVID-19 cases are ongoing." (PMID 37051252, 2023). "Indeed, targeting both C3 and C5 within the complement cascade as a way to treat COVID-19 shows promise." (PMID 35860286, 2022). "Strikingly, agents targeting C5–C5a–C5aR1 or glycosphingolipid-lowering therapies have been linked to the disruption of the SARS-CoV-2 replication and the suppression of the SARS-CoV-2-induced activation of immune inflammation in COVID-19." (PMID 36430817, 2022). "Some clinical trials could reveal if C5 blockade also works by inhibiting C5a formation and function in COVID-19." (PMID 35945604, 2022). "A general upregulation of complement system proteins, including the classical complement pathway (C1R, C1S, and C8A), the alternative pathway factor B, the complement modulators factors I and factor H, as well as MAC proteins such as C5, C6, and C8, were reflected in COVID-19 patients." (PMID 33811541, 2021). "However, more clinical trials are needed for the conclusive results of the anti-C5 antibody treatment on COVID-19 patients with AKI." (PMID 33907513, 2021). "Eculizumab, a humanized anti-C5 mAb, which is applied for paroxysmal nocturnal hemoglobinuria, atypical hemolytic uremia syndrome and neuromyelitis optica spectrum disorder, was used for four severe COVID-19 cases." (PMID 34321065, 2021). "However finding that ex vivo serum-induced C5b-9 deposition on HMEC-1 fully normalised in COVID-19 patients after eculizumab, would support an effective degree of C5 inhibition as we previously documented in patients with aHUS." (PMID 34928990, 2021). "In addition, complement factors of the terminal complement complex (TCC), C5, C6, C7, C8 and C9, were significantly increased in neutrophils from intermediate and patients with severe COVID-19." (PMID 34403366, 2021). "As the list of COVID-19-associated pathophysiology linked to deregulated complement activation grows longer, it has become clear that complement inhibitors against C3 or C5 or activating pathways open new windows of therapeutic opportunity for treatment with severe COVID-19 cases." (PMID 33811541, 2021). "Eculizumab, a terminal complement (C5)-inhibiting monoclonal antibody, was administered in five mechanically ventilated patients in life-threatening condition due to COVID-19-related acute respiratory distress syndrome (ARDS) between 23 March 2020 and 3 April 2020." (PMID 34960699, 2021). "As COVID-19 patients showed a correlation between several complement components and SOFA, we suggest that COVID-19 patients who were at high risk for immunothrombosis could be identified via elevated complement markers such as C5." (PMID 37239041, 2023).